LILRB3 (leukocyte immunoglobulin like receptor B3)
Description:
May act as receptor for class I MHC antigens. Becomes activated upon coligation of LILRB3 and immune receptors, such as FCGR2B and the B-cell receptor. Down-regulates antigen-induced B-cell activation by recruiting phosphatases to its immunoreceptor tyrosine-based inhibitor motifs (ITIM).
Synonyms: LIR-3; ILT-5; CD85a; ILT5; LIR3; HL9; PIRB; PIR-B
Tractability: Antibody: its Gene Ontology location is reachable by antibodies, with high confidence; UniProt places it where antibodies can reach, with medium confidence; UniProt predicts a signal peptide or a membrane-spanning region; the Human Protein Atlas places it where antibodies can reach.
Gene: Protein-coding gene on chromosome 19 (54,216,278 to 54,223,506, reverse strand). Ensembl gene ENSG00000204577.
Subcellular location: Cell membrane
Subcellular location (Human Protein Atlas): Plasma membrane; Cytosol
Pathways (Reactome):
Immune System: Immunoregulatory interactions between a Lymphoid and a non-Lymphoid cell; Neutrophil degranulation
Gene Ontology:
Molecular function: amyloid-beta binding; protein binding; inhibitory MHC class I receptor activity; signaling receptor activity; transmembrane signaling receptor activity
Biological process: negative regulation of osteoclast differentiation; cell surface receptor signaling pathway; cytokine-mediated signaling pathway; defense response; immune response-inhibiting cell surface receptor signaling pathway
Cellular component: plasma membrane; secretory granule membrane
Genetic constraint (gnomAD): Loss-of-function variants: 32 observed, 51.9 expected, observed/expected ratio (o/e) 0.62, 90% interval 0.46 to 0.83. The upper end of that interval is the gene's LOEUF score, 0.83, which puts it in group 3 of 6, group 1 being the genes least tolerant of losing a copy. Missense variants: 502 observed, 599.73 expected, observed/expected ratio (o/e) 0.84, 90% interval 0.78 to 0.9. Synonymous variants: 185 observed, 229.3 expected, observed/expected ratio (o/e) 0.81, 90% interval 0.71 to 0.91.
Homologues: Orthologues: chimpanzee LILRB3 (89% identical), chimpanzee LILRB3 (87% identical), macaque LILRB3 (83% identical), macaque LILRA6 (55% identical), rat Pirb (53% identical), rat Lilrb3 (43% identical), mouse Pira12 (41% identical), mouse Pira2 (40% identical), mouse Pira13 (40% identical), mouse Pira1 (40% identical), rat LOC134485274 (40% identical), mouse Lilra6 (39% identical), and 5 more. Paralogues in human: LILRB1 (70% identical), LILRA6 (68% identical), LILRB2 (64% identical), LILRB5 (63% identical), LILRA4 (52% identical), LILRA1 (49% identical), LILRA2 (49% identical), LILRB4 (48% identical), LILRA5 (28% identical), KIR3DL1 (25% identical), KIR3DL2 (25% identical), KIR3DL3 (25% identical), and 13 more.